ADH4 (alcohol dehydrogenase 4 (class II), pi polypeptide)
Diseases named in the same sentence as ADH4 in open-access papers (continued):
Sharing a sentence is not in itself a finding about the gene and the disease.
tumor (24 papers, 2016 to 2026). "explored the mechanism underlying the tumor‐suppressive effect of ADH4 and discovered the MEG3/miR664a‐3p/ADH4 axis." (PMID 39540710, 2024). "Conversely, CYP2E1 and ADH4 exhibited 3.1-fold (p=0.009) and 2.8-fold (p=0.013) decreases in tumor samples, confirming downregulation." (PMID 41164201, 2025). "For instance, decreased ADH1B and ADH4 expression in tumor cells can lead to acetaldehyde accumulation, which can promote cancer, DNA damage, and tumor growth." (PMID 41031088, 2025). "The results showed that ADH4 and C8B expression levels were downregulated in tumor tissues compared with non-tumor tissues." (PMID 38654290, 2024). "Previous research in HCC has shown a significant down-regulation of ADH4 mRNA and protein expression in tumor tissues, which shows a highly significant correlation with worse survival." (PMID 38654290, 2024). "Previous studies found that the expression of ADH4 was markedly reduced in HCC tumor tissues and identified as significant prognostic biomarker in HCC." (PMID 37957550, 2023). "Conversely, tumor suppressor genes such as Alcohol dehydrogenase 4 (ADH4) is significantly downregulated in tumor tissues, and patients with lower ADH4 expression levels have worse prognosis and lower overall survival rate." (PMID 31156698, 2019). "Network topology and machine learning approaches consistently highlighted ACACB, ADH4, and PCK1 as core hub genes, all of which showed significant differential expression between tumor and normal tissues and demonstrated strong diagnostic performance (AUC > 0.87)." (PMID 42032347, 2026). "Finally, RT-qPCR showed that all the prognostic genes except for ADH4 were under-expressed in tumor tissues." (PMID 41031088, 2025). "ADH4 was commonly expressed in the three subclusters of normal livers while it was rarely expressed in some subclusters of primary tumors and all the subclusters in metastatic lymph nodes and portal vein tumor thrombus." (PMID 38374122, 2024). "Taken together, ADH4 was simultaneously down-regulated in both HBV-positive HCC tumor tissue and HBV-positive HCC cell line, indicating that ADH4 might be a special biomarker for HBV-associated HCC." (PMID 37957550, 2023). "In addition, we explored the relationship between the TRGs risk model and TME, and revealed the strong association of METTL6, LCMT1, GSTZ1, ADH4, and ADH1A with the tumor immune infiltration and immune checkpoints." (PMID 36341373, 2022). "A few studies reported that ADH4 might be a tumor suppressor and independent prognostic factor for HCC." (PMID 34257161, 2021). "Hence, in addition to ascorbic acid, quercetin might potentiate the anti-tumor properties of BLE by down-regulating the expression of ADH4, AKR1B10 and AKR1C2, thus preventing the degradation of methylglyoxal." (PMID 27635343, 2016). "The single-cell dataset showed significant under-expression of ADH1B, ADH4, CYP19A1, and GPX3 in tumor samples." (PMID 41031088, 2025). "Results showed that four prognostic genes (ADH1B, ADH4, UGT1A1, and GPX3) exhibited significantly lower expression in tumor samples compared to normal samples." (PMID 41031088, 2025). "The other tissues also presented expressional heterogeneities of the genes (normal livers: ADH4 and PON1; metastatic lymph nodes and portal vein tumor thrombus: PON1 and NR0B1) in their hepatocyte subclusters." (PMID 38374122, 2024). "As a result, ACAT1, ADH4 and ECI1 were even more down-regulated in HBV-positive HCC tumor tissue, and ACAT1, ADH4 and ACSL3 were down-regulated in HepG2.2.15 to a higher degree." (PMID 37957550, 2023). "ADH4, GSTZ1, and ADH1A were downregulated in HCC tumor tissues compared with the normal tissues, which were consistent with their role in HCC." (PMID 36341373, 2022). "We observed that ADH4, GSTZ1, and ADH1A were downregulated in HCC tumor tissues, while the LCMT1 was overexpressed in HCC tumor tissues compared with the normal tissues, which were consistent with the mRNA expression level of HCC." (PMID 36341373, 2022).
tumor (continued). "The experimental results confirmed that ADH4 and AHNAK2 were significantly upregulated, while MMAA and DMBT1 were downregulated analogously in tumor tissues or recurrent tissues compared with controls." (PMID 35847888, 2022). "Interestingly, we observed that the expression levels of SPP2 and ADH4 were significantly lower in tumor samples compared with normal samples in the TCGA database." (PMID 40018995, 2025).
cancer (13 papers, 2015 to 2026). A tumor composed of atypical neoplastic, often pleomorphic cells that invade other tissues. "Other genes such as CYP3A4, CYP2C9, ADH4, ADH1A, and CYP1A2 enriched in the cytochrome P450 pathway are observed as metabolically active procarcinogens to genotoxic intermediates, and an association has been found between CYP enzyme activity and the risk to develop several forms of cancer." (PMID 31024618, 2019). "In this study, the suppression of ADH4, AKR1B10 and AKR1C2 genes and the subsequent encoded proteins may help to increase the intracellular methylglyoxal level which can subsequently lead to apoptosis in cancer cells." (PMID 27635343, 2016). "Our research findings indicate that ADH4 and LCAT are genes that undergo significant changes during the differentiation of hepatocytes into cancer cells." (PMID 38654290, 2024). "Consistently, the silence of METTL6 and LCMT1 decreased cancer cell migration, and depletion of GSTZ1 and ADH4 increased the cancer cell migration ability." (PMID 36341373, 2022). "Among the 7 model genes, 4 genes were differentially expressed in HCC cells and normal para-cancer tissues, namely, ANP32B, FTCD, ADH4 and PON1." (PMID 35413690, 2022). "As for the genes MMP3 and ADH4, which are identified by both indicators as inhibitory factors for cancer onset, they are both in the top 4 positions of both indicators, indicating a strong inhibitory role in the KIRC cancer onset process." (PMID 38459043, 2024). "However, FCN3, SLC22A1, ADH4, CYP2C8, SLC10A1, F9, and FBP1 were significantly downregulated in HCC tissue compared to the matched para-carcinoma tissue." (PMID 38664521, 2024). "Interestingly, all the prognostic genes except for ADH4 were under-expressed in tumors (P < 0.05), and there was no significant expression difference of ADH4 between the tumors and para-carcinoma tissues." (PMID 41031088, 2025). "The negative correlations of ADH4, PON1, and PZP expression with the IC50s of the anti-cancer drugs indicated that the LSGs might affect the efficiency of these drugs in HCC." (PMID 38374122, 2024).
adenocarcinoma (1 paper, 2024). A common cancer characterized by the presence of malignant glandular cells. "Contrarily, increased ADH4 expression has been linked to a more favorable prognosis in adenocarcinoma within non-small cell lung cancer (NSCLC)." (PMID 38654290, 2024).
ADH4 also shares sentences with these, for which no sentence is quoted: alcoholism (5 papers); non-small cell lung carcinoma (3); alcoholic fatty liver disease (2); amyloidosis (2); migraine (2); alcohol use disorder (1); alcoholic hepatitis (1); dermatitis (1); gingivitis (1); head and neck cancer (1); HIV-1 infection (1); Insulin resistance (1); melanoma (1); metabolic disorder (1); metabolic syndrome (1); Obesity (1); pancreatic adenocarcinoma (1); Parkinson (1); prostate carcinoma (1); substance abuse (1); type 2 diabetes (1); viral infection (1).